NPIPB13 (nuclear pore complex interacting protein family, member B13)
Tractability: Antibody: UniProt predicts a signal peptide or a membrane-spanning region.
Gene: Protein-coding gene on chromosome 16 (30,222,893 to 30,255,268, reverse strand). Ensembl gene ENSG00000198064.
Subcellular location: Membrane
Subcellular location (Human Protein Atlas): Nucleoplasm
Gene Ontology:
Cellular component: membrane
Homologues: Paralogues in human: NPIPB4 (99% identical), NPIPB5 (88% identical), NPIPB11 (87% identical), NPIPB12 (78% identical), NPIPB3 (36% identical), NPIPB8 (29% identical), NPIPB9 (29% identical), NPIPB6 (28% identical), NPIPB2 (27% identical), NPIPB15 (27% identical), NPIPB7 (26% identical), NPIPA2 (24% identical), and 7 more.